CD44 (CD44 molecule (IN blood group))
Description:
Cell-surface receptor that plays a role in cell-cell interactions, cell adhesion and migration, helping them to sense and respond to changes in the tissue microenvironment. Participates thereby in a wide variety of cellular functions including the activation, recirculation and homing of T-lymphocytes, hematopoiesis, inflammation and response to bacterial infection. Engages, through its ectodomain, extracellular matrix components such as hyaluronan/HA, collagen, growth factors, cytokines or proteases and serves as a platform for signal transduction by assembling, via its cytoplasmic domain, protein complexes containing receptor kinases and membrane proteases. Such effectors include PKN2, the RhoGTPases RAC1 and RHOA, Rho-kinases and phospholipase C that coordinate signaling pathways promoting calcium mobilization and actin-mediated cytoskeleton reorganization essential for cell migration and adhesion. Upon interaction with LGALS9 ligand, activates downstream signaling components including LCK, ERK and MAPK to promotes NK cell activation. (Microbial infection) Promotes foot-and-mouth disease virus internalization via macropinocytosis.
Synonyms: ECMR-III; PGP-1; LHR; MDU2; MDU3; MIC4; IN; MC56; Pgp1; CD44R; HCELL; CSPG8; Hermes-1; CDw44; HUTCH-1; HUTCH-I; ECM-III; H-CAM
Tractability: Antibody: a drug acting on it is in phase 2 or 3 trials; UniProt places it where antibodies can reach, with high confidence; its Gene Ontology location is reachable by antibodies, with high confidence; UniProt predicts a signal peptide or a membrane-spanning region; the Human Protein Atlas places it where antibodies can reach. PROTAC: ubiquitination databases record sites on it; its protein half-life has been measured; a small molecule that binds it is known. Other modalities: a drug acting on it is in phase 1 trials.
Target class: Surface antigen
Gene: Protein-coding gene on chromosome 11 (35,138,882 to 35,232,402, forward strand). Ensembl gene ENSG00000026508.
Subcellular location: Cell membrane; Cell projection, microvillus; Secreted
Subcellular location (Human Protein Atlas): Plasma membrane; Golgi apparatus; Predicted to be secreted
Pathways (Reactome):
Developmental Biology: Developmental Lineage of Mammary Gland Luminal Epithelial Cells; Developmental Lineage of Mammary Gland Myoepithelial Cells; Developmental Lineage of Mammary Stem Cells
Extracellular matrix organization: Degradation of the extracellular matrix; Integrin cell surface interactions
Immune System: Interferon gamma signaling; Neutrophil degranulation
Metabolism: Hyaluronan degradation; Hyaluronan metabolism
Hemostasis: Cell surface interactions at the vascular wall
Gene Ontology:
Molecular function: cargo receptor activity; cytokine receptor activity; hyaluronic acid binding; protein binding; signaling receptor activity; collagen binding; transmembrane signaling receptor activity
Biological process: cartilage development; cell adhesion; cell migration; cellular response to fibroblast growth factor stimulus; endocytosis; hyaluronan catabolic process; monocyte aggregation; negative regulation of apoptotic process; NK T cell activation; positive regulation of ERK1 and ERK2 cascade; positive regulation of heterotypic cell-cell adhesion; positive regulation of monocyte aggregation; regulation of lamellipodium morphogenesis; T cell activation; wound healing, spreading of cells; carbohydrate derivative transport; cell-cell adhesion; cell-matrix adhesion; inflammatory response; cytokine-mediated signaling pathway; regulation of apoptotic process; system development
Cellular component: apical plasma membrane; cell projection; cell surface; extracellular exosome; extracellular region; focal adhesion; lamellipodium membrane; macrophage migration inhibitory factor receptor complex; membrane raft; plasma membrane; basolateral plasma membrane; microvillus; secretory granule membrane; membrane; protein-containing complex
Genetic constraint (gnomAD): Loss-of-function variants: 30 observed, 62.25 expected, observed/expected ratio (o/e) 0.48, 90% interval 0.36 to 0.65. The upper end of that interval is the gene's LOEUF score, 0.65, which puts it in group 2 of 6, group 1 being the genes least tolerant of losing a copy. Missense variants: 719 observed, 788.55 expected, observed/expected ratio (o/e) 0.91, 90% interval 0.86 to 0.97. Synonymous variants: 271 observed, 276.15 expected, observed/expected ratio (o/e) 0.98, 90% interval 0.89 to 1.09.
Homologues: Orthologues: chimpanzee CD44 (98% identical), macaque CD44 (95% identical), dog CD44 (78% identical), pig CD44 (74% identical), rabbit CD44 (72% identical), mouse Cd44 (70% identical), rat Cd44 (69% identical), guinea pig CD44 (66% identical), tropical clawed frog cd44 (21% identical), zebrafish cd44b (13% identical), zebrafish cd44a (10% identical). Paralogues in human: LYVE1 (11% identical).
Diseases named in the same sentence as CD44 in open-access papers:
CD44 is named in the same sentence as 675 diseases in open-access papers, as found by Europe PMC text mining. Sharing a sentence is not in itself a finding about the gene and the disease. The quoted sentences say what the papers report.
breast carcinoma (2,035 papers, 1998 to 2026). "Over the past decades, several receptors, including HER2, CD44, and nucleolin, have been identified as overexpressed biomarkers in breast cancer, making them valuable therapeutic and diagnostic targets." (PMID 41560835, 2026). "The paper also suggested that CD44, the hallmark of breast cancer stem cells, is also post-transcriptionally regulated by β-catenin, however, interestingly only HuR was found to bind to CD44 mRNA." (PMID 40562819, 2025). "In this study, CD44 expression was associated with poor prognostic factors in breast cancer, including histological grade, tumor size, and HER2/neu status." (PMID 40881916, 2025). "In breast cancer cases, the epithelial-mesenchymal transition state is linked to a cancer stem cell-like population harboring the CD44 + /CD24- profile and has been proposed to play a critical role in metastatic progression." (PMID 40097629, 2025). "In breast cancer, a subset of CD44 overexpressing cells was linked to reduced sensitivity to chemotherapy, radiotherapy and endocrine therapy." (PMID 41168417, 2025). "This treatment in breast cancer cells resulted in increased CD44-positive EV shedding that was associated with reduced adhesion and cell spreading, favoring tumor cell invasion." (PMID 39851567, 2025). "In breast cancer cell lines, CD44 inhibition causes a decreased in CSC characteristics, invasion, and metastatic potential." (PMID 40430044, 2025). "Radiation resistance also appears closely linked to the presence of breast cancer stem-like cells marked by CD44(+)/CD24(−/low) expression." (PMID 40864743, 2025). "Resveratrol has demonstrated antimetastatic and chemo‐sensitizing effects in several malignancies, such as colorectal and breast cancers, often through modulation of CD44 and associated pathways." (PMID 40888184, 2025). "In HER2-positive breast cancer, elevated serum CD44 levels are associated with worse overall survival, whereas no such association was found in HER2-negative patients." (PMID 41440277, 2025). "CD44v6 is a splice variant of CD44, whose overexpression in many cancers, including pancreatic cancer, colon cancer and breast cancer, has been shown to confer an increased migratory and invasive capacity." (PMID 41168417, 2025). "We successfully linked the confinement‐induced emergence of a CD44+ CD133+ breast cancer cell population at the spheroid periphery to increased drug resistance." (PMID 40569213, 2025). "The CD44 gene produces multiple splice variants, including the standard isoform (CD44s) and the variable isoform (CD44v), each involved in essential roles in breast cancer development." (PMID 40563429, 2025). "Intriguingly, ablation of CD44 has already been linked with a metabolic shift from glycolysis to OxPhos in breast cancer cells." (PMID 37849446, 2024). "We investigated the associations of reproductive factors known to influence breast cancer risk with the expression of breast stem cell markers CD44, CD24, and ALDH1A1 in benign breast biopsy samples." (PMID 38577336, 2024). "LCs can also be induced by the microenvironment as a co-culture of breast cancer cells with M2-polarised tumour-associated macrophages inducing a significant increase in CD44 that corresponded with an increased proportion of the LC phenotype." (PMID 39408880, 2024). "CD44 is another cell surface glycoprotein, hyaluronate receptor, implicated in tumour stemness, recurrence, and drug resistance of ovarian and breast cancer." (PMID 39125873, 2024). "Some tumors, such as glioblastomas, express only standard CD44, while others, including gastrointestinal cancers, bladder cancer, cervical cancer, breast cancer, and non-Hodgkin lymphoma, also express CD44 variants." (PMID 38690275, 2024). "For instance, switching CD44 expression from the variant isoform (CD44v) to the standard isoform (CD44s) induced by hnRNPM protein plays a critical role in accelerating EMT in breast cancer by activating Akt signaling." (PMID 38346537, 2024).
breast carcinoma (continued). "TDP43 can regulate the alternative splicing of CD44 pre-mRNA via binding to a UG repeat sequence between CD44 pre-mRNA variant exon 10 and standard exon 6, ultimately facilitating the stemness of breast cancer stem cells." (PMID 39510185, 2024). "To further investigate this relationship, we analyzed publicly available microRNA profiles of MCF-7 breast cancer cells sorted for a surface marker phenotype commonly associated with increased stemness, CD44+/CD24–/low/ESA+." (PMID 39189967, 2024). "We then consolidated an OPN pathway and upregulated gene signatures from our findings (Spp1, Timp3, Col11a1, Mmp9, Mmp2, Fn1, Cd44, and Il-4) to interrogate how their predicted activity is associated with relapse-free survival in breast cancer patients." (PMID 39448577, 2024). "An additional subpopulation of CD44+/CD24+ cells of the BRCA1-mutated basal-A/basal-like breast cancer was sorted using an antibody against CD338 (ABCG2 antigen) and found to be enriched in several stemness markers." (PMID 36834918, 2023). "Recent studies have indicated the close association of CD44 with the metastatic ability and stemness of breast cancer cells." (PMID 37064130, 2023). "SOX2, NANOG, OCT3/4, as well as a CD44+/CD24−/low phenotype were reported to be the principal markers associated with stemness in breast cancer." (PMID 37446326, 2023). "ESRP1 was also found to suppress breast cancer stem cell function by promoting CD44 splice isoform switching from CD44s isoform that causes stemness to CD44v isoform." (PMID 38110955, 2023). "CD44 expression has been found to be higher in breast cancer cells with a more aggressive phenotype, associated with increased invasiveness and resistance to therapy." (PMID 37626666, 2023). "Summarizing the current studies, we can conclude that hnRNPM promotes the exclusion of variant exons from CD44 pre-mRNA in breast cancer." (PMID 38106992, 2023). "The marker purpose would relate to the detection of residual CD44+-associated systemic inflammation in early-stage breast cancer patients after surgery and after completion of adjuvant therapy." (PMID 36100762, 2023). "It has been found that expression of CD44v (CD44 novel splice variant) isoforms is often associated with initiation, progression, and metastasis of colon, prostate, intestinal, gastric, and breast cancers." (PMID 38002944, 2023). "For instance, differential splicing results in CD44 being expressed as a series of standard and variant isoforms, with distinct effects on breast cancer progression and metastasis." (PMID 37492150, 2023). "The cluster of differentiation 44 or CD44, as a tumor‐associated marker, can be used to detect breast cancer stem cells (BCSCs)." (PMID 36289579, 2023). "Previous work has also indicated a positive link between ROK/Gab-1 associated PI3K/AKT signalling activation during HA/CD44-mediated breast cancer progression." (PMID 37707669, 2023). "Several groups have used in vitro models to successfully propagate breast cancer CTCs and study tumor spheres after the loss of cell-matrix interactions, which revealed an increase in the stem-like CD44+CD24− population." (PMID 36979915, 2023). "Several markers have already been linked to certain types of CSCs (breast cancer: CD44+/CD24−/ALDH+; leukemia: CD34+/CD8−; liver: CD90+; pancreas: CD44+/CD24+/ESA+; epidermal surface antigen)." (PMID 35659296, 2022). "Cluster of differentiation 44 (CD44), a widely recognized marker for breast cancer stem cells (BCSCs), is extensively spliced into CD44 variant AS isoforms (CD44v) during the development of breast cancer." (PMID 35504883, 2022). "The expression of CASQ2 was further increased in mammosphere and was also associated with increased level of CD44, a well‐known marker of breast cancer stem cells." (PMID 34743414, 2022). "In hypoxic regions of breast cancer samples, an elevated expression of CD44 was observed and HIF1a appears to upregulate CD44 variants containing exons V6 and V7/8." (PMID 35406498, 2022).
breast carcinoma (continued). "Studies have implicated CD44 in breast cancer cell adhesion, proliferation, motility and migration, angiogenesis, and metastasis." (PMID 36077806, 2022). "Knockdown of CDH1 in prostate cancer cell line PC-3 caused increased expression of the CD44 gene, as initially reported in breast cancer cells." (PMID 35493092, 2022). "It was shown that the differentiation of breast cancer stem cells occurred by the knockdown of CD44 and caused the loss of the CSC phenotype along with the reduced expression of Bcl-2 and Muc-1 proteins, reducing metastasis and tumorigenesis." (PMID 35631686, 2022). "We previously reported that the dynamic expression of CD44 in breast cancers (BrCas) at collectively invading edges was associated with tumor-associated macrophages (TAMs)." (PMID 35680853, 2022). "CD44 is a common marker of breast cancer stem cells, and the association between CD44 and decreased disease-free-survival in the clinic has been widely acknowledged." (PMID 36432652, 2022). "In a meta-analysis, elevated CD44 expression has been reported in the basal subtype of breast cancer and was associated with the EMT and cancer stem cell signature." (PMID 36289750, 2022). "SMAR1 has been reported to regulate splicing of CD44 variants by deacetylation of Sam68 with help of HDAC6 in breast cancer cell lines." (PMID 33863392, 2021). "The subjects are observational studies on the relationship between rs13347 polymorphism of CD44 gene and breast cancer (including case-control study, cross-sectional study and a cohort study)." (PMID 34087833, 2021). "The current study assessed the frequency of CD44-/CD24- breast cancer cells in 576 tissue specimens for associations with clinicopathological features and metastasis and investigated the underlying molecular mechanisms." (PMID 34318746, 2021). "The CD44+/CD24− CSC population in breast cancer is associated with a mesenchymal phenotype, increased N-cadherin expression, decreased E-cadherin, and increased YAP, Twist, Snail, and Slug gene expression." (PMID 34680503, 2021). "Association of a high frequency of CD44-/CD24- cells in breast cancer tissues with delayed tumor distant metastasis." (PMID 34318746, 2021). "The COSMIC database reported 3.7% of breast cancers overexpress CD44 whilst 2.8% of breast cancer samples contain mutations in CD44." (PMID 34120626, 2021). "We identified nine cancer cell subclusters including CD44 + / ALDH2 + /ALDH6A1 + breast cancer stem cells (BCSCs), which had a copy-number variants profile similar to that of normal breast tissue." (PMID 34611125, 2021). "SMAR1 further inhibits metastasis via regulation of CD44 variants alternative splicing via HDAC6-mediated deacetylation of Sam68 in breast cancer cells." (PMID 33863392, 2021). "CD44 in breast cancer is associated with increased (P-gp) and Bcl gene expression responsible for MDR and apoptosis resistance." (PMID 33672756, 2021). "Based on the clinicopathological impact of CD44 in breast cancer basal type, it is applied as a molecular diagnostic marker, prognostic tool, therapeutic target, targeting ligand-receptor in various stages of clinical development." (PMID 33672756, 2021). "The expression of CD44 is a hallmark of BCSCs (CD44+/CD24−) in some breast cancer subtypes, in which their phenotypes, such as self-renewal, metastasis, migration and therapeutic resistance, can lead to treatment failure and disease relapse." (PMID 33801148, 2021). "Several isoforms of the human CD44 molecule are associated with tumour progression and stemness in various cancers, such as breast cancer, gliomas, head and neck squamous cell carcinoma, pancreatic cancer, prostate cancer and colorectal cancer." (PMID 34944493, 2021). "Overexpression of CD44 and its isoforms has been reported to be associated with poor prognosis in gliomas, breast cancer, pancreatic cancer, lung cancer, prostate cancer, and head and neck carcinoma." (PMID 34439211, 2021).